RAD9A (RAD9 checkpoint clamp component A)
Description:
Component of the 9-1-1 cell-cycle checkpoint response complex that plays a major role in DNA repair. The 9-1-1 complex is recruited to DNA lesion upon damage by the RAD17-replication factor C (RFC) clamp loader complex. Acts then as a sliding clamp platform on DNA for several proteins involved in long-patch base excision repair (LP-BER). The 9-1-1 complex stimulates DNA polymerase beta (POLB) activity by increasing its affinity for the 3'-OH end of the primer-template and stabilizes POLB to those sites where LP-BER proceeds; endonuclease FEN1 cleavage activity on substrates with double, nick, or gap flaps of distinct sequences and lengths; and DNA ligase I (LIG1) on long-patch base excision repair substrates. The 9-1-1 complex is necessary for the recruitment of RHNO1 to sites of double-stranded breaks (DSB) occurring during the S phase. RAD9A possesses 3'->5' double stranded DNA exonuclease activity.
Synonyms: RAD9
Tractability: Small molecule: a structure with a bound ligand is known. PROTAC: ubiquitination databases record sites on it; its protein half-life has been measured.
Gene: Protein-coding gene on chromosome 11 (67,317,871 to 67,398,410, forward strand). Ensembl gene ENSG00000172613.
Subcellular location: Nucleus
Subcellular location (Human Protein Atlas): Nucleoplasm; Nuclear bodies
Pathways (Reactome):
DNA Repair: HDR through Single Strand Annealing (SSA); Presynaptic phase of homologous DNA pairing and strand exchange; Processing of DNA double-strand break ends
Cell Cycle: Activation of ATR in response to replication stress; G2/M DNA damage checkpoint
Disease: Impaired BRCA2 binding to RAD51
Gene Ontology:
Molecular function: 3'-5'-DNA exonuclease activity; double-stranded DNA 3'-5' DNA exonuclease activity; enzyme binding; histone deacetylase binding; protein binding; protein kinase binding; SH3 domain binding
Biological process: cellular response to ionizing radiation; DNA damage checkpoint signaling; DNA damage response; DNA repair; DNA replication checkpoint signaling; mitotic intra-S DNA damage checkpoint signaling
Cellular component: checkpoint clamp complex; nuclear body; nucleoplasm; nucleus; cytoplasm
Genetic constraint (gnomAD): Loss-of-function variants: 25 observed, 40.33 expected, observed/expected ratio (o/e) 0.62, 90% interval 0.45 to 0.87. The upper end of that interval is the gene's LOEUF score, 0.87, which puts it in group 3 of 6, group 1 being the genes least tolerant of losing a copy. Missense variants: 513 observed, 523.4 expected, observed/expected ratio (o/e) 0.98, 90% interval 0.91 to 1.05. Synonymous variants: 251 observed, 212.82 expected, observed/expected ratio (o/e) 1.18, 90% interval 1.06 to 1.31.
Homologues: Orthologues: chimpanzee RAD9A (100% identical), macaque RAD9A (98% identical), pig RAD9A (90% identical), dog RAD9A (87% identical), guinea pig RAD9A (85% identical), rat Rad9a (83% identical), mouse Rad9a (82% identical), rabbit RAD9A (80% identical), tropical clawed frog rad9a (54% identical), zebrafish rad9a (49% identical), Drosophila melanogaster Rad9 (27% identical), Caenorhabditis elegans hpr-9 (24% identical). Paralogues in human: RAD9B (36% identical).